CD4 (CD4 molecule)
Diseases named in the same sentence as CD4 in open-access papers (continued):
Sharing a sentence is not in itself a finding about the gene and the disease.
ocular toxoplasmosis (5 papers, 2014 to 2025). Ocular toxoplasmosis is an infection in the eye caused by the parasite, Toxoplasm a gondii. "However, after T-cell subpopulation analysis, we found a significant increase in CD4+ central memory cell subsets expressing IFN-γ when nanoparticle was included (NP/TE) in the ocular toxoplasmosis group." (PMID 38724195, 2024). "Importantly, one group (upper left square) contained almost all individuals with ocular toxoplasmosis characterized by high IFN-γ expression (>1 log10) in CD4+ Tem, CD4+ Temra, and CD8+ Temra subsets." (PMID 38724195, 2024). "Notably, the NP/TE conjugate significantly increased the percentage of CD4+ central memory cells in the ocular toxoplasmosis group." (PMID 38724195, 2024). "As for early prognosis T. gondii-specific IL5+CD4+ T-cells and IFN-γ produced by NK-cells displayed high accuracy to define respectively ocular involvement and acute/chronic phase of ocular toxoplasmosis in infants with congenital disease." (PMID 33028847, 2020). "An antibody targeted to CXCL10 reduces the migration of CD4- and CD8-positive T cells into the retina, and promotes intraocular parasite replication and retinal damage in mouse ocular toxoplasmosis, emphasizing the role of CXCL10 in protecting the infected eye." (PMID 40137771, 2025). "Increased IFN-γ expression in CD4+ effector memory cell subsets was found in patients with ocular toxoplasmosis with NP/TE but not with TE alone." (PMID 38724195, 2024). "The analysis of CD4+ and CD8+ T-cell subset populations indicated higher IFN-γ production (>2 log10 IMFI) by the CD4+Tem subset in individuals with ocular toxoplasmosis, compared with uninfected and asymptomatic individuals, in response to either TE or NP/TE at 0.3 μg/ml stimuli." (PMID 38724195, 2024).
oedema (5 papers, 2006 to 2022). "ART initiation with consequent viral suppression, increased CD4 count, and decreased systemic inflammation have overall beneficial effects, as the markers of myocardial oedema were seen to decrease over the study term." (PMID 36529806, 2022). "Edema (P < 0.0001), skin ulcers (P = 0.0003), severe muscle weakness (dysphagia/hoarseness/soft voice, P = 0.0089; muscle strength<= grade 3, P = 0.0041), CD4 / CD8 ratio < 1.4 (P = 0.0255) and ferritin > 200 ng / ml (P = 0.0361) were considerably associated with refractory JDM." (PMID 33407621, 2021). "The novel observation of this study was that the CD4+ percentages were lower in both HIV-positive and HIV-negative children without oedema than in children with oedema." (PMID 17042940, 2006). "The novel observation of this study is that the CD4+ percentages in both HIV-positive and HIV-negative children without oedema were lower that those in children with oedema." (PMID 17042940, 2006). "Mortality was higher among males, Tanzanians, those with oedema at baseline, those not ontuberculosis medication at baseline, and increased with age, with higher C-reactive protein(CRP), with lower CD4 cell count and with lower BMI at baseline (data presented by Wooddet al.)." (PMID 28393746, 2017).
Omenn syndrome (5 papers, 2010 to 2019). An inflammatory condition characterized by erythroderma, desquamation, alopecia, chronic diarrhea, failure to thrive, lymphadenopathy, and hepatosplenomegaly, associated with severe combined immunodeficiency (SCID). "So, the hallmark for RAG deficiencies with residual T-cells, which is characteristic for Omenn Syndrome, is absence or strong reduction of naïve CD4 and CD8 T-cells." (PMID 30886612, 2019).
pituitary adenomas (5 papers, 2019 to 2025). "• The majority of infiltrating immune cells within pituitary adenomas were composed of M2 macrophages, followed by resting CD4+ memory T cells and mast cells. • NF-PitNETs had higher M2 macrophage fractions than other subtypes." (PMID 38716256, 2024). "A high expression of CCL2, CXCL10, CX3CL1, with a low number of infiltrating FOXP3 T-cells and a high number of infiltrating CD4+ T-cells was detected in highly vascularized pituitary adenomas/PitNets." (PMID 36658300, 2023). "Meanwhile, M2 macrophages also take part in the neo-angiogenesis in pituitary adenoma/PitNets, together with B cells, CD4+ T-cells and Foxp3+ lymphocytes." (PMID 36658300, 2023). "The density of infiltrated CD4+ and CD8+ T-lymphocytes may be relatively insufficient in these pituitary adenomas, but CD4+ and CD8+ T lymphocytes are significantly more in GH-secreting adenomas than non-GH adenomas." (PMID 31649621, 2019). "Some authors suggest that the infiltration of CD4+ and CD8+ T-cells is closely correlated with higher GH levels and GH-secreting adenomas exhibited significantly more T-cells than non-GH pituitary adenomas." (PMID 34501445, 2021).
posterior uveitis (5 papers, 2010 to 2022). Inflammation of the choroid as well as the retina and vitreous body. "Although posterior uveitis (affecting the posterior segment) describes a range of different clinical entities, all forms are similar immunohistologically, characterized by an infiltration of mainly lymphocytes T CD4+ (CD4+ T) cells." (PMID 20680102, 2010).
relapsing (5 papers, 2015 to 2022). "CD4+ T cells obtained from twenty-five relapsing-remitting MS patients and sixteen healthy subjects were cultured ex vivo with norepinephrine and/or β2-adrenoreceptor antagonist or agonist, followed by a cytokine production analysis using ELISA." (PMID 35054851, 2022). "Among them, miR-15a and miR-16 were previously shown to induce apoptosis by targeting BCL2 and recently lower levels of these miRNAs were found in CD4+ T cells from relapsing–remitting multiple sclerosis patients." (PMID 25366387, 2015). "Thus, the removal of pathogenic CD4+ TRM cells, in addition to CD8+ TRM cells, has the potential to break the cycle of relapsing–remitting skin diseases." (PMID 32508808, 2020). "However, more marked (~75–90%) physical depletion of CD4 T cells by CD4 and CD52 depleting antibodies inhibited relapsing disease." (PMID 27925187, 2017).
retinal degeneration (5 papers, 2020 to 2026). Degeneration of the retina. "Nevertheless, both types of T cells, cytotoxic (expressing cluster of differentiation 8, CD8+) and helper (expressing cluster of differentiation 4, CD4+), are associated with retinal degeneration." (PMID 37689689, 2023). "The coordinated dynamics of CD4+ and CD8+ T cells suggested transient immune activation during STZ-induced retinal degeneration." (PMID 42074072, 2026). "Although early evidence indicates that CD4+ and CD8+ T cell populations are related to the pathophysiology of retinal degenerations, their interactions and activation mechanisms are still unclear." (PMID 37689689, 2023). "Together, these changes led to a significantly lower ratio of CD4+/CD8+ T cells in C57Bl/6J and Cx3cr1 mice, suggesting a lymphocyte immunosenescence and active recruitment of cytotoxic T cells prior to the destructive features of retinal degeneration." (PMID 39975545, 2025). "LAMP‐1 expression did not change over time: expression of LAMP‐1 was stable in all lymphocyte compartments (P = .53 for CD4, P = .11 for CD8, P = .14 for the CD20 without the CLN3‐associated retinal degeneration subtype)." (PMID 32685355, 2020).
selenium deficiency (5 papers, 2014 to 2025). A nutritional deficiency disease resulting from inadequate selenium levels in the body, which can lead to impaired function of selenoproteins essential for antioxidant defense and thyroid hormone metabolism. "In HIV-infected patients, selenium deficiency was associated with a lower CD4 T-cell count and a shorter life expectancy." (PMID 35163318, 2022). "When we analyzed the effect of zinc or/and selenium supplementation on CD4+ T cell counts only in the individuals with baseline seric zinc or selenium deficiency, we found no significant changes on CD4+ T cells counts or frequency after supplementation (p > 0.05 in all cases)." (PMID 39351495, 2024).
seminoma (5 papers, 2013 to 2025). A radiosensitive malignant germ cell tumor found in the testis (especially undescended), and extragonadal sites (anterior mediastinum and pineal gland). "Concomitant with CD3+ T cells, the highest percentages of CD4+ Th cells (median 42.61%, range 17.03–60.69% of total live cells) were also detected in “Tumor” regions of seminoma compared to all other sites (p < 0.001)." (PMID 38649788, 2024). "Taking both median density and spatial distribution of infiltrating immune cells, i.e. disseminated infiltration, into account, CD3+ T cells, CD4+ Th and CD8+ Tc cells were more abundant in seminoma compared to embryonal carcinoma." (PMID 38649788, 2024). "IHC revealed that Tfh cells are most abundant in seminoma and localized within FLS, which also contain B cells, CD4+ Th cells, and follicular DCs." (PMID 38649788, 2024).
sinusitis (5 papers, 2009 to 2025). An acute or chronic inflammatory process affecting the mucous membranes of any sinus cavity. "In this area,dendritic cells effectively stimulate the activation of CD4+ T lymphocytes,and, associated with new stimuli (infections, environmental conditions), leads to aprofuse chronic inflammatory process causing a sinusitis crisis." (PMID 20379688, 2010).
Sleep apnea (5 papers, 2021 to 2025). An intermittent cessation of airflow at the mouth and nose during sleep is known as sleep apnea. "To address this gap, we first investigated and compared the percentages and phenotypes of CD4+ and CD8+ Treg cell subsets in tonsils and peripheral blood cells derived from the same individuals with sleep apnea, with an average age of approximately 40 years." (PMID 39806065, 2025). "Patients with sleep apnea have been found to have higher CD8+ T lymphocyte levels, CD4+/CD8+ ratios, and humoral immune-related indices, such as interleukins 4, 6, and 10 and interferon-γ." (PMID 33808734, 2021).
thrombotic thrombocytopenic purpura (5 papers, 2015 to 2024). "The other symptomatic patient had a history of thrombocytopenic thrombotic purpura (ITP) without dysgammaglobulinemia, with normal levels of B and NK cells, an increase in T follicular helper cells, and a reduction in CD4/CD8 T-cell ratio." (PMID 35566429, 2022).
thyroid nodule (5 papers, 2017 to 2025). A small circumscribed mass in the THYROID GLAND that can be of neoplastic growth or non-neoplastic abnormality. "Our analysis of thyroid nodules classified as C-TIRADS category 3 or higher revealed a distinct pattern in CD4+ T-cell distribution." (PMID 40895621, 2025).
tongue cancer (5 papers, 2015 to 2023). A malignant neoplasm affecting the tongue. "A tongue cancer study indicated that malignant transformation was accompanied by an increase in CD4+ and B cells, in addition to CD8+ and CD14+ cells." (PMID 36009387, 2022). "Neutrophils, CD8+ and CD4+ lymphocytes infiltrate tongue carcinomas, and infiltrating immune cells produce pro-inflammatory cytokines." (PMID 26176534, 2015). "In tongue cancer, the percentages of CD3(+) cells, CD3(+) CD4(+) cells, NK cells, and the CD4(+)/CD8(+) ratios after an operation were significantly lower in the sevoflurane groups, while propofol exhibited a better effect on the recovery of immunity." (PMID 36408275, 2022).
toxic epidermal necrolysis (5 papers, 2007 to 2022). Toxic epidermal necrolysis (TEN) is an acute and severe skin disease with clinical and histological features characterized by the destruction and detachment of the skin epithelium and mucous membranes. "Recently, it has also been shown that, besides in toxic epidermal necrolysis (TEN), granulysin is also expressed by CD4 and CD8 T cells and natural killer (NK) cells in different drug reactions including AGEP, suggesting that granulysin may also play a role in the pathogenesis of AGEP." (PMID 27472323, 2016).
trachoma (5 papers, 2013 to 2025). "CD4 T cells are involved in the wound healing response, and have also been implicated in pathogenesis of conjunctival scarring in conjunctival cicatrizing disorders such as trachoma and ocular pemphigoid." (PMID 31822709, 2019). "It has been shown that T cells, particularly CD4+ T cells, and the Th2 response correlate with scarring trachoma both locally and systemically." (PMID 39093884, 2024). "Biopsies from children with active trachoma show heavy cellular infiltrates with both CD4+ and CD8+ lymphocytes." (PMID 23457650, 2013). "The role other types of CD4+ T cells play in trachoma pathogenesis has received little attention." (PMID 23457650, 2013). "While we were able to measure variations in conjunctival CD4+ and CD8+, further studies are warranted to more precisely define their implication in the immune response to trachoma." (PMID 39093884, 2024).
upper respiratory tract infection (5 papers, 2011 to 2025). "In case of upper respiratory tract infection, CD4+ T cells assist in driving the B cell-dependent autoantibody response and modulating the activation and elimination of CD8+ T cells." (PMID 28257632, 2017). "In our study, we found that angular cheilitis and papular pruritic eruptions were significant predictors of CD4 cell count <250cells/mm3 while angular cheilitis and recurrent upper respiratory tract infections predicted a CD4 cell count <350 cells/mm3." (PMID 21589912, 2011). "This is the first study to demonstrate the utility of the angular cheilitis, papular pruritic eruptions and upper respiratory tract infections in identifying HIV patients with low CD4 cell count which would improve on the sensitivity of the clinical staging guidelines." (PMID 21589912, 2011). "Angular cheilitis and papular pruritic eruptions were found to be significant predictors of CD4 cell count <250cells/mm3 while angular cheilitis and recurrent upper respiratory tract infections were found to be significant predictors of CD4<350cells/mm3 in multivariate analysis." (PMID 21589912, 2011). "For this purpose, IL-2 expression at its gene and protein levels and quantitation of CD4+ and CD8+ T lymphocytes were assessed in children aged 0-5 years old suffering from upper respiratory tract infection with S. pyogenes and healthy children of the same age." (PMID 27493590, 2016). "Angular cheilitis and papular pruritic eruptions and recurrent upper respiratory tract infections may be used, in addition to the WHO staging, to improve sensitivity in the interim, as access to CD4 machines increases in Uganda." (PMID 21589912, 2011).
urothelial carcinoma (5 papers, 2020 to 2025). A malignant neoplasm derived from the transitional epithelium of the urinary tract (urinary bladder, ureter, urethra, or renal pelvis). "The significantly lower rate of PD‐L1‐positive tumor cells and macrophages, as well as of intratumoral CD8‐positive and CD4‐positive lymphocytes, M2 macrophages, and dendritic cells in MTAP‐deficient urothelial carcinomas is consistent with more efficient immune evasion in these tumors." (PMID 39668577, 2025).
uterine corpus endometrial carcinoma (5 papers, 2020 to 2025). A endometrial carcinoma (disease) that involves the body of uterus. "In the TIMER2.0 database, there was a positive association between RBM15 and CD4 + T-cell infiltration in uterine corpus endometrial carcinoma (CESC), but the correlation coefficient was only 0.156." (PMID 37474926, 2023). "The results showed that the high expression of ACE2 of uterine corpus endometrial carcinoma in enriched B cells (HR = 0.24), enriched CD4+ memory T cells (HR = 0.28), enriched CD8+ T cells (HR = 0) and enriched macrophages (HR = 0.09) cohort had better prognosis respectively." (PMID 32339157, 2020). "Similarly, ACE2 has a positive correlation with B cell (r=0.166, p<0.01), CD4 + T cell (r=0.154, p<0.01), neutrophil (r=0.223, p<0.001) and dendritic cell (r=0.271, p<0.001) immune infiltration levels of uterine corpus endometrial carcinoma." (PMID 32339157, 2020).
acute liver failure (4 papers, 2017 to 2022). Rapid deterioration of liver function causing encephalopathy and coagulopathy. "As a consequence, increased MDSC in the inflamed liver specifically restrained the local proliferation of infiltrated pathogenic CD4+ T cells, and thus protected against the inflammation-induced acute liver failure." (PMID 31481966, 2019).
acute-on-chronic liver failure (4 papers, 2012 to 2021). Acute-on-chronic liver failure (ACLF) is an extreme condition during the natural history of chronic HBV infection, with a relatively high short-term mortality. "T-helper 17 (Th17) and CD4+CD25+ T-regulatory (Treg) cells play important roles in the pathogenesis of hepatitis B virus-related acute-on-chronic liver failure (HBV-ACLF)." (PMID 34869773, 2021). "It is not universally agreed that there is a relationship between CD4+CD25+ Treg frequency and the severity of acute-on-chronic liver failure (ACLF)." (PMID 22978653, 2012).
Adrenal insufficiency (4 papers, 2013 to 2023). Insufficient production of steroid hormones (primarily cortisol) by the adrenal glands. "Only a relatively small number of patients showed that CD4+ cell count is not a predictor for the presence or absence of adrenal insufficiency." (PMID 37627941, 2023).
allergic bronchopulmonary aspergillosis (4 papers, 2015 to 2021). Allergic bronchopulmonary aspergillosis (ABPA) is a rare immunologic pulmonary disorder caused by hypersensitivity to Aspergillus fumigatus, clinically manifesting with poorly controlled asthma and recurrent pulmonary infiltrates. "Finally, by RT-PCR, we determined RORγt and IL-17a gene expression in FACS- sorted lung eosinophils and CD4+ T cells from wild-type and IL-23p19-/- mice with allergic aspergillosis." (PMID 34464425, 2021). "In contrast, in patients with allergic bronchopulmonary aspergillosis (ABPA), A. fumigatus-specific Th2 CD4+ T cells are predominant and a recent work has identified SNPs in genes related with Th2 responses like IL13 and IL4R that increase ABPA susceptibility." (PMID 30459771, 2018).
amebiasis (4 papers, 2008 to 2020). A parasitic infectious disorder caused by amoebas. "In fact, none of these two infections is currently considered as opportunistic, even though HIV infection was reported to increase the risk of developing invasive amoebiasis and symptomatic G. intestinalis infection with progressive immunosuppression following reduced CD4 cell counts." (PMID 24662743, 2014). "Neither invasive amoebiasis nor high-titre IHA was associated with CD4 lymphocyte counts at baseline." (PMID 32530918, 2020). "In univariate analysis, patients acquiring amebiasis were predominantly MSM and had significantly higher CD4 counts than those who remained uninfected (315 vs. 157 cells/L; p<0.001) (data not shown)." (PMID 18301730, 2008).
Anorexia (4 papers, 2014 to 2022). Lack of desire to eat (loss of appetite). "The association persisted after adjusting for age, fatigue, dyspnea, anorexia, hemoglobin, neutrophil, lymphocyte, D-dimer, procalcitonin, BNP (Brain Natriuretic Peptide) and T cell subsets (CD3+, CD4+, CD8+)." (PMID 34112103, 2021).
anxiety disorder (4 papers, 2018 to 2023). A category of psychiatric disorders which are characterized by anxious feelings or fear often accompanied by physical symptoms associated with anxiety. "The study found that CD3 and CD4 values were higher in patients with anxiety disorders alone than in unaffected controls." (PMID 36835652, 2023). "Sociodemographic and clinical factors significantly associated with anxiety disorders in this study were as follows: age of child, caregiver distress (indicated by the SRQ-20 score), current CD4 count of the CA-HIV, and caregiver religion." (PMID 35572346, 2022). "In patients with anxiety disorders, both CD3 and CD4 are increased." (PMID 36835652, 2023). "Lifetime anxiety disorder also was less likely among women who were working than not working [OR 0.6 (0.4–0.8)], and more likely among women with CD4 cell counts higher than 200 [OR 1.5 (1.0–2.3)]." (PMID 29460130, 2018).